IL27 (interleukin 27)
Diseases named in the same sentence as IL27 in open-access papers (continued):
Sharing a sentence is not in itself a finding about the gene and the disease.
acute myeloid leukemia (8 papers, 2013 to 2025). Acute myeloid leukemia (AML) is a group of neoplasms arising from precursor cells committed to the myeloid cell-line differentiation. "For example, IL-27 treatment decreased proliferation and expression of angiogenesis and invasion-related genes in human pediatric acute myeloid leukemia (AML) cells in vitro." (PMID 28255204, 2017). "For example, IL-27 directly inhibits proliferation and angiogenesis in B cell lymphoma, acute lymphoblastic leukemia, acute myeloid leukemia and multiple myeloma cells." (PMID 26657115, 2015). "Similarly, acute myeloid leukemia cells injected into NOD/SCID/IL-2Rγ−/− mice gave rise to leukemia dissemination that was severely inhibited by IL-27." (PMID 24155891, 2013). "Elevated levels of IL-27 have been reported in certain malignancies, including melanoma and acute myeloid leukemia (AML)." (PMID 41296385, 2025). "In contrast to pediatric leukemias, a study has shown that IL-27 improves survival of adult Acute Myeloid Leukemia (AML) cells and decreases their responsiveness to chemotherapeutic agents." (PMID 30581461, 2018).
Insulin resistance (8 papers, 2017 to 2025). Increased resistance towards insulin, that is, diminished effectiveness of insulin in reducing blood glucose levels. "After injection of IL-27, obese mice showed significant weight loss,reduced fat accumulation, improved insulin resistance and hepatic steatosis.IL-27 plays a key role in the regulation of metabolic processes, but there are scarce data on circulating IL-27 levels in hypothyroidism." (PMID 37600722, 2023). "IL27 has been implicated in insulin resistance in genome wide association studies." (PMID 35840765, 2022). "Beyond its function in modulating the equilibrium between pro-inflammatory and anti-inflammatory responses, IL-27 also plays a crucial role in enhancing thermogenesis, preventing diet-induced obesity, and ameliorating insulin resistance." (PMID 40969371, 2025). "Thus, it was hypothesized that IL-27 may improve fatty liver by improving insulin resistance and reducing blood lipids." (PMID 37600722, 2023). "Therefore, the findings support previous observations that IL-27 could improve insulin resistance and reduce fat accumulation." (PMID 37600722, 2023). "IL-27-IL-27Rα signaling promotes thermogenesis, prevents DIO, and improves insulin resistance." (PMID 38536726, 2024).
metastatic tumors (8 papers, 2012 to 2024). "Taken together, the current evidences suggested that IL-27 can inhibit both primary and metastatic tumor, which potentially makes it a valuable therapeutic agent in poorly immunogenic tumors." (PMID 25170932, 2014). "IL-27-expressing vectors have been shown to exhibit potent anti-tumor activity in malignancies and metastatic tumors." (PMID 22827855, 2012). "Suppression of mast cells by IL-27/cabo can potentially inhibit metastatic tumor growth." (PMID 37842640, 2023). "Analyses of patient data from the Cancer Genome Atlas (TCGA) showed that GIMAP6, SAMD9L, and IL27 are significantly upregulated in metastatic tumors compared to the primary lesions, whereas TAP1 was not differentially expressed in patient samples." (PMID 38719996, 2024).
Neonatal sepsis (8 papers, 2020 to 2026). Systemic inflammatory response to infection in newborn babies. "In a murine model of neonatal sepsis, mice deficient in IL-27 signaling exhibited reduced mortality, increased weight gain, and better control of bacteria with reduced systemic inflammation." (PMID 40977737, 2025). "The diagnostic validity of IL-6, IL-8, IL-10 and IL-27 for neonatal sepsis were investigated in several cross-sectional studies and meta-analyses." (PMID 38027268, 2023). "In a murine model of neonatal sepsis, mice deficient in IL-27 signaling exhibit reduced mortality, increased weight gain, and better control of bacteria with reduced systemic inflammation." (PMID 36891292, 2023). "Previous studies have demonstrated that cytokines such as IL-6, IL-8, IL-10, and IL-27 were biomarkers of neonatal sepsis and their diagnostic properties have been investigated." (PMID 38027268, 2023). "Collectively, our results suggest that IL-27 represents a therapeutic target to limit susceptibility and improve infectious outcomes in neonatal sepsis." (PMID 31818960, 2020). "Meta-analysis results showed that the pooled sensitivity of IL-27 for diagnosing neonatal sepsis was 0.82 [95% confidence interval (CI), 0.77-0.87], which was significantly higher than that of CRP (0.73; 95% CI, 0.65-0.79)." (PMID 42212107, 2026). "The data presented in this body of work suggested that KCs in neonatal sepsis are leading IL-27 producers based on their abundance amongst the GFP+ population." (PMID 40682363, 2025). "Presently, we dissected the IL-27 producer profile at a single-cell level using IL-27p28eGFP reporter mice in our previously established model of neonatal sepsis with luciferase-expressing K1-encapsulated Escherichia coli." (PMID 40682363, 2025). "We have determined that the cytokine interleukin (IL)-27 is expressed at elevated levels in the first days of life and continues to rise during experimental bacterial neonatal sepsis." (PMID 40130859, 2025). "This study defines mechanisms that improve the host response in the absence of IL-27 signaling during neonatal sepsis and reinforces the potential for antagonizing IL-27 as a host-directed therapy for neonatal sepsis." (PMID 40977737, 2025). "Phenotypic changes are observed in our neonatal sepsis model that are consistent with an increase in IL-27 gene expression during systemic infection." (PMID 36891292, 2023). "Superiority index of IL-8, IL-10, and IL-27 were 1.84 (0.20, 5.00), 1.04 (0.20, 5.00), and 2.21 (0.20, 5.00) in the detection of late-onset neonatal sepsis." (PMID 38027268, 2023). "Interleukins including IL-6, IL-8, IL-10, and IL-27 demonstrated favorable performance in the detection of neonatal sepsis." (PMID 38027268, 2023). "Results of ANOVA model revealed that the superiority index of IL-6, IL-8, IL-10, and IL-27 were 1.20 (0.14, 5.00), 5.14 (0.33, 7.00), 0.75 (0.14, 5.00), and 1.31 (0.14, 5.00) in the detection of early-onset neonatal sepsis." (PMID 38027268, 2023). "In the detection of late-onset neonatal sepsis, IL-8 showed the highest sensitivity, and IL-27 demonstrated the highest specificity." (PMID 38027268, 2023). "IL-27 has been suggested as a biomarker for critically ill children and more recently declared a biomarker for early-onset neonatal sepsis (EONS)." (PMID 31818960, 2020). "Neonatal sepsis studies from our group using IL-27Rα-deficient (KO) mice, revealed that absence of IL-27 signaling improved maintenance of body mass, increased bacterial clearance with reduced systemic inflammation, and decreased mortality rates in the pups." (PMID 40977737, 2025). "Findings of this network meta-analysis suggest that interleukins including IL-6, IL-8, IL-10, and IL-27 may have favorable performance in the detection of neonatal sepsis." (PMID 38027268, 2023). "IL-27 was more accurate in the detection of late-onset neonatal sepsis." (PMID 38027268, 2023). "This period is consistent with peak serum IL-27 levels in our model of neonatal sepsis." (PMID 36891292, 2023).
Neonatal sepsis (continued). "To determine if IL-27 levels continue to rise during infection and how the cytokine may impact the host response, we established a murine model of neonatal sepsis." (PMID 31818960, 2020). "To advance IL-27 neutralization as a potential intervention strategy in the clinic for neonatal sepsis, we have to understand the characteristics of the cells that produce IL-27, the tissues that these cells are derived from, and how they may interact in the host response to infection." (PMID 40682363, 2025). "A reduced inflammatory response in the absence of IL-27 may seem counterintuitive given many literature precedents, but our results suggest that the direct influence of IL-27 on bacterial killing by phagocytes is the dominant mechanism that dictates outcomes during neonatal sepsis." (PMID 31818960, 2020). "Indeed, IL-27 has been proposed as a biomarker for neonatal sepsis." (PMID 31818960, 2020). "This study revealed that STAT-3 is necessary for IL-27 suppression of macrophage-mediated bacterial killing, but neither myeloid-specific nor global STAT-3 inhibition during neonatal sepsis achieves the same outcome as loss of IL-27 signaling." (PMID 40130859, 2025). "Our findings were consistent with a recent report that described the negative influence of IL-27 on protective immunity and the clearance of bacteria during neonatal sepsis." (PMID 34208904, 2021).
pneumonia (8 papers, 2015 to 2025). An acute, acute and chronic, or chronic inflammation focally or diffusely affecting the lung parenchyma, caused by an infection in one or both of the lungs (by bacteria, viruses, fungi, or mycoplasma.). "Elevated circulating levels of IL-27 have also emerged as an unfavorable prognostic marker in critically ill patients, including patients with pancreatitis and pneumonia." (PMID 41302192, 2025). "Little is currently known about the role of IL-27 in pneumonia." (PMID 25651926, 2015). "Notably, the vascular endothelial marker IL-6 was significantly upregulated in the eight pneumonia cases, and IL-27, which negatively regulates inflammation, was also activated, suggesting that IL-6 may be an important marker of disease severity of psittacosis." (PMID 36119044, 2022).
prostate tumors (8 papers, 2014 to 2023). "In the present report, we have examined the impact of exogenous IL-27 as an immune-modulating therapy for prostate tumors in cell culture and in vivo." (PMID 34209203, 2021). "We chose sonodelivery because we have recently utilized this strategy to achieve partial antitumoral responses for IL-27, whereas intratumoral rIL-18 has yielded partial antitumor responses when administered directly to prostate tumors." (PMID 34209203, 2021). "We tested single or sequential IL-27 and IL-18 therapies both in cells and in vivo, finding significant promise for the sequential 27→18 method for prostate tumors." (PMID 34209203, 2021). "We detected an increase in the phosphorylated form of eIF2α and in the cleaved caspase-3 fraction, indicating the eIF2α signaling pathway is upregulated in these prostate tumor cells following targeted IL-27 gene delivery, leading to apoptosis induction." (PMID 32046108, 2020). "We detected an increase in the phosphorylated form of eIF2α and in the cleaved caspase-3 fraction, indicating that the eIF2α signaling pathway was upregulated in these prostate tumor cells following targeted IL-27 gene delivery, leading to apoptosis induction." (PMID 32046108, 2020). "We detected an increase in the phosphorylated form of eIF2α and in the cleaved caspase-3 fraction, indicating that the EIF2 signaling pathway was upregulated in these prostate tumor cells following targeted IL-27 gene delivery." (PMID 32046108, 2020). "BLI showed that the combination of cabo and IL-27 inhibited prostate tumor growth in the bone." (PMID 37842640, 2023). "We have hypothesized that cytokine Interleukin-27 (IL-27) is an excellent candidate biologic to help rebalance the prostate tumor cells and bone cell environment." (PMID 35200430, 2022). "Overall, we found that the sequential approach (IL-27 or 27pepL-targeted) allows one to flexibly incorporate both gene delivery and recombinant cytokines as tools to augment a cytokine’s bioactivity and efficacy against prostate tumors." (PMID 34209203, 2021). "This cytokine sequencing approach allows flexible incorporation of both gene delivery and recombinant cytokines as tools to augment IL-27’s bioactivity and reengineer efficacy against prostate tumors and may prove applicable in other therapeutic settings." (PMID 34209203, 2021). "Although our previous work indicated that IL-27 could inhibit prostate tumor growth, one limitation was that tumors only showed ~50% growth reduction compared to controls." (PMID 34209203, 2021). "We therefore hypothesized that the efficacy of our IL-27 gene delivery protocol for prostate tumors could be augmented if combined with IL-18 administration, especially if administered sequentially." (PMID 34209203, 2021). "In terms of IL-27, gene therapy of IL-27 could efficiently reduce prostate tumor cell growth in mice." (PMID 28746469, 2017). "No study of IL-27 on bladder cancer has been reported, but IL-27 has been reported to be effective in reducing tumor growth and can promote enhanced accumulation of effector cells in prostate tumors." (PMID 26014498, 2015). "We previously examined a first-generation IL-27 targeted at the C-terminus with a short ‘peptide L’ (pepL, LSLITRL), which binds the interleukin 6 receptor α (IL-6Rα) that is upregulated in tumor cells in order to reduce prostate tumor growth (IL-27pepL or 27pepL)." (PMID 35200430, 2022). "In another recent report, we discovered the promise of a new IL-27 cytokine, targeted at the C-terminus with a short ‘peptide L’ (pepL, LSLITRL), which binds the interleukin 6 receptor α (IL-6Rα) upregulated in tumor cells for reducing prostate tumor growth (IL27pepL or 27pepL)." (PMID 34209203, 2021).
pulmonary fibrosis (8 papers, 2015 to 2025). Chronic progressive interstitial lung disorder characterized by the replacement of the lung tissue by connective tissue, leading to progressive dyspnea, respiratory failure, or right heart failure. "In a mouse model of pulmonary fibrosis, NETs were found to antagonize the production of the anti-fibrotic cytokine IL-27 in macrophages, exacerbating tissue remodeling and fibrosis." (PMID 40109341, 2025). "Previous studies have shown that interleukin-27 (IL-27) can reduce bleomycin (BLM)-induced pulmonary fibrosis (PF)." (PMID 36869378, 2023). "Overexpression of DNMT1, knockdown of lncRNA MEG3, autophagy inhibitor or ERK/p38 signaling pathway inhibitors reversed the positive effect of IL-27 in a lung fibrosis model in vitro." (PMID 36869378, 2023). "A study conducted in vivo suggested that IL-27 production can aggravate bleomycin-induced pulmonary fibrosis in mice." (PMID 34975300, 2022). "Previous studies have indicated that multiple cytokines, including TGF-β1, IL-1β, TNF-α, IL-17, IL-27, IL-13, and IL-32, are overexpressed in pulmonary fibrosis." (PMID 33097029, 2020). "In this study, we identified potential molecular mechanisms of the effects of IL-27 on pulmonary fibrosis." (PMID 26932661, 2016). "We previously established that IL-27 is involved in pulmonary fibrosis in a bleomycin-induced mouse model, but the specific mechanism was not determined." (PMID 26932661, 2016). "Although IL-27 has been shown to potently inhibit lung fibrosis, the detailed mechanism of IL-27 in this process is poorly understood." (PMID 26932661, 2016). "To further explore the mechanism of IL-27 in pulmonary fibrosis, we examined the role of IL-27 in EMT of A549 cells." (PMID 26932661, 2016). "In this study, we observed the expression of IL-27/IL-27R in a mouse model of bleomycin (BLM)-induced pulmonary fibrosis." (PMID 25888222, 2015). "To explore the role of IL-27 in the pathogenesis of pulmonary fibrosis, we assessed IL-27/IL-27R mRNA expression in BIPF using quantitative RT-PCR." (PMID 25888222, 2015). "This study demonstrates that IL-27 potentially attenuates BLM-induced pulmonary fibrosis by regulating Th17 differentiation and cytokine secretion." (PMID 25888222, 2015). "In this experiment, our results indicate that IL-27 attenuates pulmonary fibrosis by regulating T cell differentiation and the secretion of IL-17 and other cytokines." (PMID 25888222, 2015). "To investigate the mechanism by which IL-27 acts in pulmonary fibrosis, we determined JAK, STAT1, STAT3, STAT5, and SOCS3 protein levels as well as STAT1, STAT3, and STAT5 phosphorylation levels using Western blot analysis." (PMID 25888222, 2015). "Our results suggest that the JAK/STAT signalling pathway might be a key molecular mechanism of IL-27 activity in pulmonary fibrosis." (PMID 26932661, 2016). "Our previous work demonstrated that IL-27 might inhibit Th17 cell differentiation and the secretion of related inflammation factors in a bleomycin-induced pulmonary fibrosis model." (PMID 26932661, 2016). "IL-27 also enhances the survival of mice with pulmonary fibrosis." (PMID 25888222, 2015). "Increased IL-27 expression in BLM-induced pulmonary fibrosis was noted." (PMID 25888222, 2015). "The results verified that IL-27 alleviates pulmonary fibrosis." (PMID 25888222, 2015). "In addition, IL-27 potentially inhibits the pulmonary fibrosis by regulating T cell differentiation and the secretion of IL-17 and other cytokines and suppressing the JAK/STAT and TGFβ1/SMAD signaling pathways." (PMID 25888222, 2015). "In this study, our data demonstrate that IL-27 possesses variable functions in pulmonary fibrosis." (PMID 25888222, 2015). "For instance, the two studies found an inhibitive role of IL-27 in fibrosis, and BLM-induced pulmonary fibrosis mice may correlate with the effects of IL-27 on inhibiting Th2 and Th17 cells and related inflammatory cytokines and promoting the differentiation of Treg cells." (PMID 38566992, 2024).
pulmonary fibrosis (continued). "IL-27 treatment may alleviate pulmonary fibrosis and increase the survival of mice." (PMID 25888222, 2015). "Therefore, we speculate that IL-27 may inhibit pulmonary fibrosis by influencing the expression of inflammatory factors." (PMID 25888222, 2015). "At present, the role of IL-27 in pulmonary fibrosis remains unknown." (PMID 25888222, 2015). "Our results increase the current understanding of IL-27 in EMT and identify new potential targets for therapeutic intervention of pulmonary fibrosis." (PMID 26932661, 2016). "Currently, the role of IL-27 in idiopathic pulmonary fibrosis is not clearly defined." (PMID 26932661, 2016).
systemic sclerosis (8 papers, 2012 to 2025). A chronic disorder, possibly autoimmune, marked by excessive production of collagen which results in hardening and thickening of body tissues. "In systemic sclerosis, IL-27-MSC likely suppress TGF-β signaling through TSG-6, reducing collagen deposition and cutaneous fibrosis while improving vascular dysfunction and Raynaud’s phenomenon." (PMID 40642057, 2025). "In contrast, another study revealed that IL-27 was elevated and could strongly induce IL-17 production in systemic sclerosis patients." (PMID 34744512, 2021). "Finally, high circulating IL-27 concentrations are observed in patients with systemic sclerosis, and IL-27 stimulation of skin fibroblasts induced proliferation and collagen synthesis, implying a possible role for IL-27 in the fibrotic pathology of this disease." (PMID 31156640, 2019).
ulcerative colitis (8 papers, 2013 to 2024). An inflammatory bowel disease involving the mucosal surface of the large intestine and rectum. "The role of IL-27 in ulcerative colitis (UC) also demonstrates dual functionality, exhibiting both anti-inflammatory and pro-inflammatory effects depending on the context." (PMID 39906735, 2024). "In ulcerative colitis, IL-27 demonstrates protective and anti-inflammatory characteristics, though its effects may be influenced by genetic and environmental factors." (PMID 39906735, 2024).